IL4 (interleukin 4)
Diseases named in the same sentence as IL4 in open-access papers (continued):
Sharing a sentence is not in itself a finding about the gene and the disease.
respiratory infections (9 papers, 2010 to 2025). "The function of IL-4 in Ch. pneumoniae respiratory infection during early life and its association with AHR and AAD development require further analysis." (PMID 34226412, 2021). "We observed that IL-4 is linked with Chlamydia respiratory infection and its absence lowers respiratory infection." (PMID 34226412, 2021). "One single-nucleotide polymorphism from IL4 gene was significant for pooled respiratory infections (rs2070874; 1.66 [1.29–2.14])." (PMID 26524966, 2015). "In the present study, it is observed that the level of IL-4Rα2 is suppressed by Ch. pneumoniae respiratory infection which enables the IL-4 in promoting further infection and severity of AAD." (PMID 34226412, 2021). "Further studies are needed to characterize how air pollutants can induce IL-4 during respiratory infections." (PMID 21092162, 2010). "In spite of these reports, the underlying mechanism of IL-4 is not properly understood with respect to respiratory infection." (PMID 34226412, 2021). "Interestingly, in the pinworm (-) group, after correction for possible confounding factors including recent gastroenteritis and respiratory infection with oral medication (and possible antibiotics usage), an inverse correlation between Collinsella abundance and gut IL-4 level was detected." (PMID 28945752, 2017). "Other studies have demonstrated the immunomodulatory activity of B. clausii, reducing the expressions of IL-4, IFN-γ, IL-12, TGF-β and IL-10 in allergic children with recurrent respiratory infections." (PMID 39770518, 2024).
tetanus (9 papers, 2014 to 2023). A serious infectious disorder that follows wound contamination by the Gram-positive bacterium Clostridium tetani. "In fact, this concept appears to already have been validated for TfH2 cells, since blocking of IL-4 caused a profound block in Th2-class switch and improved antibody responses to oxycodone and diptheria-pertussis-tetanus vaccination." (PMID 32294982, 2020). "We find that offspring born to mothers infected with S. mansoni have impaired production of IL-4 during homeostasis, and following immunization with a Tetanus-Diphtheria vaccine." (PMID 33524040, 2021). "This is likely tied to the reduction in IL-4 secretion in the germinal center reaction, as our recent work demonstrated that tetanus and diphtheria have a differential dependence on IL-4 for IgG1 class switching." (PMID 33524040, 2021). "Our synthesized Ac2PIM6 has comparable adjuvant activity with the natural PIMs against ovalbumin and tetanus toxoid antigens and induced the production of interleukin-4 and interferon-γ, thus, validating the immunological qualities of PIM molecules and its value in vaccine research." (PMID 26037164, 2015). "These defects in follicular dendritic cells and IL-4 production were maintained long-term with reduced secretion of IL-4 in the germinal center and reduced generation of TFH, memory B, and memory T cells in response to immunization with tetanus/diphtheria." (PMID 33524040, 2021). "The production of 9 cytokines (IFN-γ, TNF-α, IL-2, IL-4, IL-10, IL-17, IL-21, TGF-β, GM-CSF) following in vitro stimulation of PBMCs with tetanus and diphtheria toxoid was analyzed, and was found to be similar in young and elderly adults." (PMID 27602049, 2016). "It was particularly interesting to observe a high increase of IgG2 that has been described to correlate with IgG4 responses to tetanus vaccine in autoantibody negative children, and both subclasses correlated with IL-4 and IL-13 secretion." (PMID 30009185, 2018).
ulcer (9 papers, 2010 to 2025). "The cell-mediated type 2 (Th2) immune response and interleukin-4 (IL-4) and IL-5 production increase significantly, accompanied by weight loss, diarrhea, ulcers, and a decreased number of colorectal epithelial cells." (PMID 38790796, 2024). "Immunoblotting results confirmed that the ethanol-induced ulcer control group exhibited significant reductions in IL-4 (5.96-fold) level and increases of NF-κB p65 (10.50-fold), TNF-α (2.66-fold), and MCP-1 (3.06-fold) levels compared to the normal group." (PMID 28587230, 2017). "In this context, the ulcer healing effect of sucralfate is partially the result of rapid mucosal IL-4 generation that leads to suppression of mucosal apoptotic events." (PMID 25610477, 2014). "L. major-infected BALB/c mice display a persistent Th2 response with high levels of IL-4 and IL-13 in contrast to C57BL/6 mice and develop ulcerative skin lesions." (PMID 37908348, 2023). "However, AMHAE pretreatment displayed significant increases of IL-4 (6.92-fold) and HSP-70 (4.57-fold) levels and a decline of NF-κB p65 (2.62-fold), TNF-α (2.66-fold), and MCP-1 (6.63-fold) levels compared to the ethanol-induced ulcer control group." (PMID 28587230, 2017).
acute kidney injury (8 papers, 2015 to 2025). Sudden and sustained deterioration of the kidney function characterized by decreased glomerular filtration rate, increased serum creatinine or oliguria. "Some studies have shown that IL-4 deficiency exacerbates acute kidney injury and cerebral ischaemia injury, with an increase in M1 macrophages and a decrease in M2 macrophages." (PMID 32258110, 2020). "Ori has been shown to ameliorate acute kidney injury by inhibiting macrophages-mediated inflammation, and suppressing the expression of cytokines IL-2, IL-4, IL-6, IL-10, and TNF-α, suggesting that Ori had a potent anti-inflammatory response activity." (PMID 37375489, 2023). "Mice with normal numbers of NKT cells had higher levels of cytokine early after treatment IL-2, IL-4, IFN-γ, and IL-17 in mouse kidney with subsequent renal failure as well as urine abnormality." (PMID 25904903, 2015). "Other studies have reported the induction of IL-6 expression during the development of acute kidney injury both in humans and in experimental animal models; however, a study of IL-4 expression was not performed." (PMID 31583036, 2019).
allergic contact dermatitis (8 papers, 2014 to 2026). An inflammatory skin condition caused by an immune response to direct contact between the skin and an allergen. "Among the cytokines whose levels increased with worsening of Allergic contact dermatitis, a significant increase in the expression of Il4 and Il13 was observed." (PMID 41488203, 2026). "FITC-mediated CHS in mice has been characterized as an animal model of allergic contact dermatitis mediated by a Th2-dominant immune system: high amounts of IL-4 were expressed at the protein level in the inflamed ear, and plasma IgE levels were increased." (PMID 24498391, 2014).
appendicitis (8 papers, 2017 to 2025). Acute inflammation of the vermiform appendix. "In ALF, the highest concentrations of IL-4 and IL-13 were present in complicated appendicitis, perforated appendicitis and peritonitis, which are associated with more destructive forms of appendicitis (unpublished data)." (PMID 38673802, 2024). "This cohort study aimed to evaluate the association of serum concentrations of IgE, IL-4, IL-9, and IL-13 in children with the risk of complicated appendicitis." (PMID 35586830, 2022). "The aim of the present study was to evaluate whether concentrations of IgE and the Th2-associated cytokines interleukin (IL)-4, IL-9 and IL-13 in serum are associated with the risk of complicated appendicitis in children." (PMID 35586830, 2022). "Here, we propose the concept of appendicular lavage and use it to study the levels of the Th2 cytokines IL-4, IL-5, and IL-9 in patients with a clinical diagnosis of acute appendicitis." (PMID 31772507, 2019). "Serum concentrations of IL-4 and IL-9 did not affect the risk of complicated appendicitis, but at the same time high levels of IL-13 were associated with an increased risk of complicated appendicitis." (PMID 38673802, 2024). "Serum concentrations of IgE, IL-4, and IL-9 did not significantly affect the risk of complicated appendicitis." (PMID 35586830, 2022). "High concentrations of serum IL-13 seem to be associated with an increased risk of complicated appendicitis in children, while serum total IgE, IL-4 and IL-9 do not seem to be associated with the risk of complicated appendicitis." (PMID 35586830, 2022). "However, in contrast to our finding, the cytokine IL-4 has been found to be elevated in mild appendicitis when compared with the more severe form." (PMID 34677379, 2021). "IgE, IL-4, and IL-9 concentrations did not affect the risk of complicated appendicitis in the crude or the adjusted analysis: IgE aOR 0.53 (95% CI 0.329–1.181, p = 0.12), IL-4 aOR 1.08 (95% CI 0.59–1.99, p = 0.81), and IL-9 aOR 1.05 (95% CI 0.93–1.19, p = 0.46)." (PMID 35586830, 2022). "When comparing the expression of IL-4 between Group II and Group III, a 2.7-fold increase was observed depending on the clinical and morphological forms of acute appendicitis, with significantly higher levels in the gangrenous and perforated forms." (PMID 38397914, 2024). "When comparing phlegmonous appendicitis values with those of NPA, the difference was significant (p = 0.01): IL-4 (48.3 vs. 21.3 pg/mL), IL-5 (29.2 vs. 8.0 pg/mL), and IL-9 (34.1 vs. 16.6 pg/mL)." (PMID 36499410, 2022). "The difference was more pronounced when comparing phlegmonous appendicitis with nonpathological appendicitis (p = 0.01) for IL-4 (48.3 vs. 21.3 pg/mL), IL-5 (29.2 vs. 8.0 pg/mL), and IL-9 (34.1 vs. 16.6 pg/mL)." (PMID 31772507, 2019). "The results of our study show a statistical difference in the levels of IL-4 between phlegmonous and nonpathologic appendicitis." (PMID 31772507, 2019). "Differences in IL-4, IL-5, and IL-9 in AL fluid were found between the 3 study groups and especially significant between phlegmonous and negative appendicitis." (PMID 31772507, 2019).
bullous pemphigoid (8 papers, 2018 to 2026). Bullous pemphigoid (BP) is the most common form of autoimmune bullous dermatosis. "We found that, similar to the spontaneous form of bullous pemphigoid (BP), interleukin-4 (IL-4) and interleukin-13 (IL-13) were upregulated." (PMID 40507326, 2025). "Its efficacy has extended to other Th2-driven dermatoses including prurigo nodularis and bullous pemphigoid, highlighting the central role of IL-4/IL-13 in these diseases." (PMID 41226755, 2025). "Dupilumab, a monoclonal antibody blocking the receptor binding of interleukin-4 (IL-4) and interleukin-13 (IL-13), has been successfully used to treat spontaneous forms of bullous pemphigoid (BP)." (PMID 40507326, 2025). "- Bullous pemphigoid displays a clear Th2-mediated inflammatory response, characterized by IL-4, IL-5, and IL-13, eosinophil recruitment and pruritus." (PMID 41479908, 2025). "IL‐4/−13 contribute to itch in bullous pemphigoid with dupilumab being evaluated in clinical trials." (PMID 36477831, 2023). "Our review identified keratinocytes as crucial mediators in bullous pemphigoid, predominantly orchestrating Th2-driven inflammation through secretion of cytokines including IL-16, leading to CD4+ T cells recruitment and amplification of the IL-4/IL-13 axis." (PMID 41479908, 2025).
cerebral malaria (8 papers, 2012 to 2024). A sequestration of Plasmodium falciparum in the brain, which can cause coma and/or seizures. "A study conducted among Ghanaian children showed that carriers of both IL-4−590*T and IL-4+33*T alleles presenting cerebral malaria had elevated IgE compared to non carriers." (PMID 23668806, 2013). "Two studies demonstrated a trend toward lower IL-4 levels in cerebral malaria; meanwhile, other studies demonstrated a trend toward higher IL-4 levels in cerebral malaria." (PMID 35820892, 2022). "IL-4 has been incriminated in the aggravation of cerebral malaria due to its role in an increase in parasite mass, in an infiltration by monocytes, basophils, and eosinophils and an increase in parasite sequestration." (PMID 23668806, 2013). "Furthermore, regardless of genotype, relative levels of cytokines, particularly the ratio of IL4 to IFNG, are more strongly associated with protection from cerebral malaria than levels of any single cytokine alone." (PMID 25192715, 2014). "In particular, the balance of inflammatory Type I cytokines, such as interferon gamma (IFNG) and tumour necrosis factor (TNF), with Type II cytokines, e.g., interleukin 4 (IL4) and IL10, is thought to determine the lethality of cerebral malaria." (PMID 25192715, 2014). "Absence of IL-4 in mice are protected from cerebral malaria and mice treated with IL-4 analogous were protected against development of cerebral malaria by decreasing parasitaemia levels, inflammation and decreasing levels of cytotoxicity of T-cells." (PMID 39482779, 2024). "IL-33 protects against experimental cerebral malaria by driving the expansion of ILC2s and their production of IL-4, IL-5 and IL-13 and is required for ILC2-derived IL-13- but not IL-4-driven Type 2 responses during hookworm infection." (PMID 28168040, 2017).
Chronic colitis (8 papers, 2016 to 2023). A chronic inflammatory disease of the large intestine (colon, cecum and rectum). "Studies have shown that improvements following LcS treatment on DSS-induced chronic colitis were associated with a decrease in IFN-γ production and an increase in IL-4 production in LI-LPMC, when stimulated with CD3ε/CD28." (PMID 27500935, 2016). "Moreover, SSW might decrease the expressions of IFN-γ, IL-1β, and IL-17, upregulate the level of IL-4, and show therapeutic effects in chronic colitis." (PMID 34956391, 2021). "The level of IL-4 and IL-5 with anti-CD3 and anti-CD28 mAb stimulation and without any stimulation was markedly increased in the IL-33-treated chronic colitis group compared with the control group." (PMID 30539029, 2018). "It is worth noting that our results revealed an increase in the levels of IL-10 and IL-4 in non-treated chronic colitis rats." (PMID 37513865, 2023).
fascioliasis (8 papers, 2012 to 2025). A parasitic infection that is caused by liver flukes, usually Fasciola hepatica, of sheep, goats, and cattle. "Moreover, the depletion of eosinophils during experimental fasciolosis was associated to a decreased production of IL-4, IL-5 and IFNγ, suggesting that in the absence of eosinophils the Th2 or Th1 immune responses are impaired." (PMID 33042162, 2020). "Thus, the ratio of IL-4–producing MCs in counted MCs infiltration in EPP cattle (24.4%) was 3 times more than in fascioliasis cattle (8.1%)." (PMID 36605763, 2022). "The immune response mounted during the early stages of fasciolosis is generally a mixed Th1/Th2 response with elevated levels of cytokines such as IFN-γ, IL-4, IL-10, and TGF-β." (PMID 38149297, 2023). "The immune response exerted during the early stages of fasciolosis is generally regarded as a mixed Th1/Th2 response displaying an increase of certain cytokines such as IFN-γ, IL-4, IL-10, and TGF-β." (PMID 38149297, 2023). "Cattle with Fascioliasis only, had significantly higher serological levels of IFN-γ, IL-1, IL-2, IL-4, and IL-18 than control and CE single infected cattle." (PMID 32915902, 2020). "In a mouse study with experimental Fasciola infection, spleen cells from BALB/c exhibited a Th2 response, producing high levels of the cytokines IL-4 and IL-5, and low levels of IFN-gamma and IL-2." (PMID 22938392, 2012). "In EPP, the mast cells increased as well as in fascioliasis, and the mast cells producing tryptase without chymase increased with interleukin-4 production." (PMID 36605763, 2022). "However, the number of IL-4–producing MCs per 1 mm2 of EPP cattle (182.5 ± 75.2, n=10) was significantly higher than that in fascioliasis cattle (58.2 ± 21.2; n = 6, P = 0.0392, one-way ANOVA, two-tailed test) or healthy cattle (63.1 ± 37.5; n = 5, P = 0.0461, one-way ANOVA, two-tailed test)." (PMID 36605763, 2022).
gingivitis (8 papers, 2014 to 2026). A disorder involving inflammation of the gums; may affect surrounding and supporting structures of the teeth. "In addition, part of SIgA may combine with T cells in the body, and as a result, cause secretion of cytokines, such as TGF-β, IL-4 and IL-10 to strengthen local immune function and further mobilize the body’s own immune response to gingivitis." (PMID 34234776, 2021). "Salivary cytokine profile differed according to oral condition: caries was associated with reduced IL-4, IL-10, and IFN-γ; gingivitis with elevated IL-1Ra and RANTES; and both conditions with increased IL-1β (p-value < 0.05)." (PMID 41505053, 2026). "The disproportionate salivary levels of IL‐1β and IL‐4 in patients with gingivitis are likely to be the molecular signature of oral inflammation, possibly induced by increasing phosphate consumption." (PMID 35141474, 2022). "The present study uncovered that T2DM increased the level of IL-7 in GCF of patients with gingivitis, while the IL-4 level was decreased." (PMID 33417619, 2021). "Results of the present study revealed significantly higher levels of SIgA in saliva as well as TGF-β, IL-4 and IL-10 in plasma of gingivitis patients, relative to healthy controls, suggesting enhanced local humoral immunity." (PMID 34234776, 2021). "We explored levels of Th17/Treg-related cytokines, targeting TGF-β, IL-4, IL-6, IL-10 and IL-17, using ELISA, and found that all cytokines were significantly elevated in the gingivitis patients, relative to healthy controls." (PMID 34234776, 2021). "However, TGF-β mRNA as well as TGF-β, IL-4, IL-6, IL-10 in the periperial blood and SIgA in the saliva were higher in the gingivitis group." (PMID 34234776, 2021). "Similarly, after adjusting for age, sex, body mass index, and gingival redness, the daily dietary phosphate consumption was strongly correlated with the salivary level of IL‐1β; it was inversely correlated with the salivary level of IL‐4 in patients with gingivitis." (PMID 35141474, 2022). "In subjects with gingivitis, compared with the Cg group, levels of inflammatory factors IFN-γ, IL-4, IL-5, IL-6, IL-10 and IL-13 were significantly lower in saliva in the Dg group (p<0.05)." (PMID 33417619, 2021).